INS (insulin)
Diseases named in the same sentence as INS in open-access papers (continued):
Sharing a sentence is not in itself a finding about the gene and the disease.
diabetes (continued). "WHtR was significantly associated with age (p < 0.05), management of diabetes by OHA (p < 0.05) and insulin (p < 0.05) in this analysis." (PMID 25113234, 2014). "In vivo and in vitro studies have demonstrated the insulin-mimetic properties of selenium and have indicated that appropriate dietary supplementation with selenium can prevent diabetes." (PMID 24983750, 2014). "Thiazolidinediones (TZDs) were approved for type 2 diabetes mellitus (DM) treatment based on efficacy studies, which showed a decrease in HbA1c, by 0.8-1.5% and improved insulin sensitivity." (PMID 24708579, 2014). "Although there are several other successful drugs that have been administered to the systemic circulation by inhalation, the best example of the expanding role of aerosol therapy into systemic drug delivery is treating diabetes with oral inhalation of insulin." (PMID 25505695, 2014). "In this regard, it has been described that some probiotics can improve the resistance to insulin in different animal models of diet-induced diabetes or with different genetic backgrounds." (PMID 24971309, 2014). "A program supporting the initiation of insulin therapy in primary care was introduced in Belgium, as part of a larger quality improvement project on diabetes care." (PMID 25145469, 2014). "Diabetes is one of the most common metabolic disorders, characterized by defective secretion of insulin." (PMID 25105142, 2014). "Studies of multiple countries have reported that insulin autoantibody (IAA) takes an important role in diabetes prediction." (PMID 24629100, 2014). "Similar to melatonin, insulin in the brain also regulates the metabolism, molecular composition, and cognitive performance of microcircuits and reduces food intake; cerebral insulin levels are altered in diabetes, aging, obesity, and Alzheimer's disease." (PMID 27355037, 2014). "Clinicians that treat individuals with diabetes (especially those treated with insulin) should be taught to incorporate fracture prevention into the current list of interventions they offer to diabetic patients." (PMID 24919660, 2014). "Recently, cardiotrophin-1, a member of the interleukin-6 family of cytokines was described to protect beta-cells from apoptosis, to improve glucose-stimulated insulin secretion and insulin resistance, and to prevent streptozotocin-induced diabetes in mice." (PMID 25025664, 2014). "The bioactive lipid 5-HEPE is known to be a potent agonist of GPR119 and enhances glucose-dependent insulin secretion, suggesting the molecule as a possible biomarker candidate for diabetes." (PMID 24632803, 2014). "Exercise is another important part of managing diabetes because it improves insulin action, reduce weight, decrease glucose intolerance and the occurrence of complications." (PMID 24885315, 2014). "Diabetes in Cocker Spaniels showed an association with three SNPs from three different genes: MTTL1 (rs24305581), PAX4 (rs22302353) and INS (rs22686871) and in the miniature Dachshund there was a single association with HNF4A (rs8804236)." (PMID 26401325, 2014). "GTT’s were performed in 109 subjects with exclusion of a total of 41: 24 with normal glucose and insulin curves; 11 with glucose impairment (fasting blood sugar ≥100 mg/dL, 2 hour ≥140 mg/dL or both); 4 with overt diabetes; and 2 with incomplete data." (PMID 25259787, 2014). "This is of particular importance when studying pathologies such as diabetes mellitus, where impaired muscle metabolism is known to play an important role in the development of insulin sensitivity and cardiovascular complications are common." (PMID 24610788, 2014). "The resulting cell mass of one monkey spleen would be enough to perform autologous cell transplantation after differentiation of the PCMO to insulin-producing cells and induction of diabetes in the monkey." (PMID 24932602, 2014).
diabetes (continued). "Type 2 diabetes mellitus (T2DM), a risk factor for vascular dementia, is a heterogeneous metabolic disease characterized by reduced insulin sensitivity and relative insulin deficiency." (PMID 24860814, 2014). "Type 2 diabetes mellitus is the consequence of an increase in the production of glucose in the liver and a deficit in the secretion and action of insulin." (PMID 24808896, 2014). "It is also likely that Imatinib treatment improves diabetes through different mechanisms working together, e.g. providing β cell survival signals and at the same time promoting insulin production." (PMID 24835010, 2014). "In people with type 2 diabetes (the commonest type of diabetes) blood sugar control fails because the fat and muscle cells that normally respond to insulin become insulin resistant." (PMID 25181492, 2014). "As a result of this unique mechanism, alpha-glucosidase is effective for patients even if they have a comparatively long duration of diabetes and a severe deterioration of insulin secretion." (PMID 24684803, 2014). "By the time an individual starts insulin therapy, diabetes-related complications are already likely to be present due to poor blood sugar control." (PMID 23599736, 2013). "Thiazolidinediones (TZDs), the insulin-sensitizing drugs, antagonize TNFα-induced lipolysis in adipocytes, thereby increasing insulin sensitivity in diabetes patients." (PMID 23951179, 2013). "The MH policy for pre-procedural medication management in fasting patients with diabetes was also established and involved omitting morning dose of oral hypoglycemics, short-acting, and pre-mixed insulin on the day of the procedure when fasting from midnight." (PMID 24223574, 2013). "We found significant differences between the groups (SVDG (−) versus SVGD (+)) with respect to the active smokers rate, the prevalence, and duration of diabetes treated with insulin." (PMID 24151618, 2013). "Thirty two of the participants were taking oral hypoglycemic agents for their diabetes control, one subject was controlled with insulin and twelve were receiving combination therapy with insulin and oral hypoglycemic agents." (PMID 23734746, 2013). "Since all of the identified common diabetes risk loci of the MTNR1B gene are outside of the coding sequences, the mechanism controlling how genetic variation affects insulin secretion and glucose homeostasis remains poorly understood." (PMID 23535335, 2013). "We showed that tamoxifen (TAM)-induced deletion of Glis3 in adult animals leads to acute downregulation of insulin production, hyperglycaemia and subsequently beta cells apoptosis and fulminant diabetes." (PMID 23197416, 2013). "In the present study, we clearly demonstrated that family history of diabetes can be a strong prenatal factor for predicting the insulin requirement in GDM." (PMID 23976911, 2013). "A decline in mortality rates from neoplasms and cardiovascular diseases (CVDs) was also found during the study periods among non-insulin-treated persons with diabetes." (PMID 23837500, 2013). "Expression of FGFR4 in liver was found to be decreased by fasting, increased by insulin, and reduced by streptozotocin-induced diabetes, implicating FGFR4 as a primary target of insulin regulation." (PMID 23922646, 2013). "Elevated levels of serum insulin as well as non-esterified FFAs in the obese state decrease insulin sensitivity and increase insulin resistance in metabolic tissues, including liver, muscle and adipose tissue, leading to type 2 diabetes mellitus." (PMID 24391749, 2013). "Combination of anti-CD20 with oral insulin was ineffective in reversing diabetes in NOD mice whose glycemia was controlled with SC insulin pellets; these experiments were performed in three independent labs." (PMID 23405091, 2013). "“To me, insulin is good for our health because it can control blood sugar and prevent amputation and dialysis” (2 years of insulin use/ 5 years of having diabetes)." (PMID 24164794, 2013).
diabetes (continued). "The attenuation in the rise of insulin in the avocado inclusive intervention is worthy of future exploration in persons with insulin resistance and type 2 diabetes mellitus to determine if avocado intake can favorably influence measures of glucose homeostasis." (PMID 24279738, 2013). "It has also been employed as an adjunct to lifestyle modifications in pre-diabetes and insulin-resistant states." (PMID 23415113, 2013). "Type 2 diabetes mellitus (T2DM) results from a progressive insulin secretion defect on the background of insulin resistance, leading to the loss of glycemic control and eventual diabetes complications, such as diabetic nephropathy (DN)." (PMID 24369464, 2013). "Six of the top ten pathways have direct linkage with diabetes, including one carbon pool by folate, arachidonic acid metabolism, insulin signaling pathway, amino sugar and nucleotide sugar metabolism, propanoate metabolism, and starch and sucrose metabolism." (PMID 23369247, 2013). "The beneficial effects of CZ In-vivo includes; a) attenuation of weight loss associated with diabetes, b) reduction of Fasting Blood Glucose, c) reducing LDL and increasing HDL cholesterol, d) reducing HbA1c and e) increasing circulating insulin levels." (PMID 24148965, 2013). "In a meta-analysis comparing TAC vs. CsA as the primary immunosuppressant for kidney transplant recipients, TAC-treated patients were two to three times more likely to develop new diabetes mellitus that required insulin." (PMID 24275847, 2013). "Pharmacist-led CSII services appear to improve diabetes control in patients requiring intensive insulin therapy." (PMID 27536441, 2013). "Insulin-producing cells (IPCs) from pluripotent stem cells offer the potential to treat diabetes by providing a source for injured pancreatic beta cells without the limitations of current therapeutic modalities." (PMID 23421382, 2013). "By the time diabetes is diagnosed, β-cells attempt to secrete sufficient insulin to overcome the insulin resistance in a process that involves islet hyperplasia." (PMID 24137248, 2013). "One of the most frequent diabetes-related complications as a result of insulin treatment is fall in blood glucose (Hypoglycemia)." (PMID 24171891, 2013). "Better knowledge of physiopathology of diabetes, availability of new insulin and devices, as well as education of health care providers are considered as important factors for improving self-care in children and adolescents with diabetes." (PMID 24171891, 2013). "The positive feedback, comprised of insulinPI3KAKT1FOXOPDX1insulin, helps -cell mitigate the difference between the demand and supply of insulin at the initial stage of diabetes." (PMID 24244124, 2013). "Beta cell dysfunction signals an advanced state of diabetes as insufficient insulin is secreted to meet demand." (PMID 23542897, 2013). "MSCs can be differentiated into insulin producing cells (IPCs) and their possible therapeutic potential for diabetes depends upon this differential ability." (PMID 23648189, 2013). "The primary action of glyburide in diabetes is to reduce blood glucose concentration by stimulating insulin secretion by the β-islet cells of the pancreas." (PMID 24147174, 2013). "Insulin degludec (IDeg) is an ultra-long-acting basal insulin in clinical development for the treatment of type 2 and type 1 diabetes mellitus (T2DM and T1DM)." (PMID 23130654, 2013). "Cross-sectional studies using the ADDQoL have also shown that patients with diabetes have poor QoL, especially those that are obese, those with type 1 diabetes, those using insulin, and those with diabetes related complications." (PMID 24349036, 2013). "As diabetes progresses, insulin sensitivity and beta cell function decline; albeit, the mechanisms of reductions are not fully understood." (PMID 31667005, 2013). "Defective insulin action in the skin has been proposed as an important mechanism contributing to wound healing defects in diabetes." (PMID 23484099, 2013).
diabetes (continued). "Diabetes mellitus is a group of metabolic diseases characterised by hyperglycaemia, resulting from defects in insulin secretion, insulin action or both." (PMID 24217303, 2013). "Diabetes develops when there is deterioration in β-cell insulin secretory responsiveness to glucose due to β-cell failure." (PMID 23886319, 2013). "Subjects with diabetes detected by HbA1c only had lower TG, lower systolic blood pressure, higher insulin sensitivity and were less insulin resistant and more physically active as compared to subjects with diabetes detected by OGTT only." (PMID 23365572, 2013). "“Well, I’ve got diabetes, which I take insulin for and I’ve got high blood pressure and I suffer from chest problems...The thing is they treated me for asthma but now they’ve decided it’s not that, it’s gosh I forget what it is, some kind of breathing problem." (PMID 23509869, 2013). "Adiponectin, a hormone derived from the adipose tissue, has been demonstrated to have insulin-sensitizing and anti-inflammatory properties in obesity and type 2 diabetes mellitus." (PMID 23840093, 2013). "Type 2 diabetes mellitus (T2DM) is a group of metabolic diseases characterized by hyperglycemia resulting from a progressive insulin secretory defect with insulin resistance." (PMID 23536853, 2013). "In this subgroup analysis, a statistically significant reduction for any diabetes-related complication was still observed in patients treated with rapid-acting insulin analogues." (PMID 24244557, 2013). "Administration of streptozotocin caused rapid destruction of pancreatic cells in rats, which led to impaired glucose-stimulated insulin release and insulin resistance, both of which are marked feature of diabetes." (PMID 24010048, 2013). "The president of the Association for Diabetes Care Professionals (EADV) in her interview likewise claimed that “the diabetes care nurse is thé expert in the field of adjusting and regulating insulin”." (PMID 24124613, 2013). "In the context of T1D a recent study demonstrated that low doses of a high affinity insulin peptide mimetope was more effective at preventing diabetes than the native peptide." (PMID 24367363, 2013). "Our depressed patients tended to be older in age, to have a longer duration of diabetes and a higher percentage were receiving insulin treatment." (PMID 23410093, 2013). "In this context clinicians should avoid over-reduction of insulin and other diabetes medications when initiating GLP-1 RA combination therapy in poorly controlled patients (as discussed 43)." (PMID 23061470, 2013). "Diabetes affects the expression of many candidate genes in the insulin dependent peripheral tissues like liver, adipose, and skeletal muscles." (PMID 23840254, 2013). "That is why (this) information is very important to ease the acceptance to insulin therapy” (3 years of insulin use/ 8 years of having diabetes)." (PMID 24164794, 2013). "This provides a measure of β-cell function adjusted for insulin sensitivity and is predictive of diabetes." (PMID 23991163, 2013). "The glucose intolerance in correspondence with the impairment of the insulin secretion was observed in male LEA, suggesting that the main cause of diabetes in LEA rats is hypoinsulinemia attributable to a decreased number of β-cells in the islets." (PMID 23691528, 2013). "Therapeutic plans for managing non-insulin requiring diabetes are: anecdotal and historical (often), evidence-based (infrequently) or outcome based (rarely)." (PMID 23841986, 2013). "Postpartum OGTT revealed diabetes mellitus (2 h plasma glucose >200 mg/dL) with low blood insulin values (5–23.6 mU/mL), C-peptide 1.1 ng/mL, and anti-GAD Ab positivity (>2000 U/L), while HbA1c was 5.9%." (PMID 23606858, 2013). "Participants in this study believed that using insulin therapy meant their diabetes status was worse." (PMID 24719629, 2013).
diabetes (continued). "Diabetes mellitus is a group of metabolic diseases characterized by chronic hyperglycemia resulting from defects in insulin secretion, insulin action, or both." (PMID 23367498, 2013). "Insulin deficiency is the initiating event that induces decreases in insulin signaling cascade in the brain and contributes to diabetes-induced cognitive deficits." (PMID 23638297, 2013). "Understanding the complex mechanism of ceramide action in diabetes requires adequate knowledge of insulin signal transduction and sphingolipid biosynthesis." (PMID 23835113, 2013). "Patients with a shorter duration of diabetes were more likely to achieve glycemic control and discontinue insulin for diabetes control at the 1-year follow-up (P < .05 for trend)." (PMID 24011395, 2013). "Eighty-nine diabetic pregnant women treated with a basal insulin (ILPS or NPH) were consecutively recruited from January 2008 to August 2010 in two diabetes units in Rome (S. Andrea and Sandro Pertini)." (PMID 23840206, 2013). "At the same time, diabetes-related technology is evolving with medical devices such as insulin pumps offering several alternatives to physicians and patients." (PMID 27536441, 2013). "Relatively few diabetic individuals in Japan are obese, and impairment of insulin secretion often develops before onset of diabetes." (PMID 23691528, 2013). "In type 2 diabetes, a non-insulin dependent diabetes mellitus, the body retains some endogenous insulin secretory capability; however, their insulin levels are low relative to their blood glucose levels and/or there is a measure of insulin resistance." (PMID 23641947, 2013). "Currently, beside insulin, the most widely used medications for diabetes are insulin and the oral hypoglycemic drugs." (PMID 24383002, 2013). "Perhaps, they also thought that insulin use was less traumatic then they initially anticipated as claimed by the diabetes patients in Phillips (2007)." (PMID 24164794, 2013). "Main cost categories in patients with on average 11 years of diabetes duration were costs for glucose self-monitoring, insulin pump therapy, hospitalization and insulin." (PMID 23967077, 2013). "It is possible, based on existing evidence that starting insulin substitution in the latter subpopulation of women may delay the development of subsequent disturbances in carbohydrate metabolism and thus may partly reduce future cardiovascular risk related to diabetes." (PMID 23819910, 2013). "Reactive oxygen species (ROS)-induced pancreatic β cell death has an important role in the pathogenesis of diabetes and also affects insulin secretion." (PMID 23408741, 2013). "This study was designed to assess the effect of maternal diabetes in rats on serum glucose and insulin concentrations, insulin resistance, histological architecture of pancreas and glycogen content in liver of offspring." (PMID 23998129, 2013). "It has recently been outlined that diabetes duration, use of insulin, the bariatric procedure performed and, presumably, preoperative BMI, all contribute to the wide variability of remission rates reported." (PMID 23537494, 2013). "As not every subject with type 2 diabetes benefits from intensive glycemic control, flexible regimens of treatment with diabetes drugs (including insulin) are needed for reaching individualized glycemic goals." (PMID 23721170, 2013). "Another factor to be considered is that diabetes per se is a metabolic disease in which fuels metabolism is perturbed given the rupture of one of the most important anabolic axis of the organism: insulin/insulin-like growth factor type-I." (PMID 23484099, 2013). "Human fetal pancreatic progenitor cells have good capacity for generating insulin producing cells and provide a promising potential source for diabetes treatment." (PMID 24268157, 2013).